IGF2BP2 (insulin like growth factor 2 mRNA binding protein 2)
Diseases named in the same sentence as IGF2BP2 in open-access papers (continued):
Sharing a sentence is not in itself a finding about the gene and the disease.
ovarian carcinoma (continued). "Quite recently, 2 RNA-binding proteins (RBPs)—FXR1 and IGF2BP2—were identified as key signal transduction mechanisms altered by niclosamide in ovarian cancer." (PMID 37259418, 2023). "FXR1 and IGF2BP2 were thus suggested as direct targets of niclosamide with a critical role in driving multiple oncogenic pathways in ovarian carcinoma." (PMID 37259418, 2023). "Especially, the m6A “reader” IGF2BP2 gene was predominantly amplified with a frequency of 18% in ovarian cancer and the high amplification rate of IGF2BP2 was also reported in other cancers." (PMID 34149801, 2021). "Further investigations are warranted to confirm the role of IGF2BP2-mediated fate regulation of m6A modified RNA in ovarian cancer." (PMID 34149801, 2021). "GSEA analysis demonstrated that the expressions of METTL3, YTHDC1, RBM15B, HNRNPC, IGF2BP2, RBMX, and ZC3H13 were correlated with a higher number of multiple Hallmark pathways in ovarian cancer." (PMID 33225598, 2021). "The results showed that high expression of ALKBH5 and IGF2BP2 was associated with a poorer prognosis both in OS and PFS analysis in ovarian cancer, which might be due to its high expression in M2 macrophages in ovarian cancer microenvironment." (PMID 38637813, 2024). "However, we found that the expression of IGF2BP2 was mainly expressed in granulosa cells and smooth muscle cells, its expression in the macrophages of ovarian tissues and ovarian cancer tissues in single-cell level analysis were relative very low." (PMID 38637813, 2024). "However, few studies have focused on the role of ALKBH5 and IGF2BP2 in regulating macrophage polarization in ovarian cancer." (PMID 38637813, 2024). "However, the expression of IGF2BP2 was relatively low in macrophages in ovarian cancer microenvironment." (PMID 38637813, 2024). "In addition, to investigate the relationship between M2 macrophages with ALKBH5 and IGF2BP2 in ovarian cancer, two independent datasets from GEO database using CIBERSORT method were searched for further study." (PMID 38637813, 2024). "Taken together, our results could potentially represent the roles of ALKBH5 and IGF2BP2 played in macrophages in ovarian cancer, which might work as the potential immunotherapy biomarkers." (PMID 38637813, 2024). "Moreover, a ternary complex consisting of circITGB6, IGF2BP2, and FGF9 has been shown to promote TAM polarization to the M2 phenotype, which is associated with tumor-promoting activities in ovarian cancer." (PMID 39596216, 2024). "Furthermore, we tried to investigate the role of ALKBH5 and IGF2BP2 played in macrophages in ovarian cancer." (PMID 38637813, 2024). "However, we found that the expression level of IGF2BP2 was much lower than ALKBH5 in ovarian cancer immune microenvironment." (PMID 38637813, 2024). "Furthermore, we investigated the prognostic role of ALKBH5 and IGF2BP2 in ovarian cancer, which both showed the overexpression of ALKBH5 and IGF2BP2 represented the worse prognosis for ovarian cancer." (PMID 38637813, 2024). "IGF2BP2 was also found to be overexpressed in epithelial ovarian cancers." (PMID 19832977, 2009). "Besides, circITGB6 was bound to IGF2BP2 to promote ovarian cancer cisplatin resistance." (PMID 41439029, 2026). "However, the expression of IGF2BP2 was very low in immune cells in ovarian cancer microenvironment." (PMID 38637813, 2024). "However, the expression level of IGF2BP2 in ovarian cancer immune microenvironment was very low." (PMID 38637813, 2024). "Interestingly, the autoantibody against IGF2BP1 was also detected at a comparable percentage (26.5%), and it is unknown whether the autoimmune responses to IGF2BP1 and IGF2BP2 are correlated in ovarian cancer patients." (PMID 29736175, 2018). "In ovarian cancer, the study showed that circITGB6 can directly interact with IGF2BP2 and FGF9, thus stabilized FGF9 and promoted M2 polarization in ovarian cancer." (PMID 38637813, 2024).
ovarian carcinoma (continued). "Consistent with our results, IGF2BP2 and IGF2BP3 were significantly increased in ovarian cancer, whereas FTO was significantly decreased in ovarian cancer." (PMID 38714753, 2024). "Ovarian cancer patients with higher expression of ALKBH5 and IGF2BP2 showed worse prognosis, possibly because of their close correlation with immune response." (PMID 38637813, 2024). "In ovarian cancer, the knockdown of circ-0001756 could suppress IGF2BP2 mediated RAB5A expression, thus inhibiting malignant progression of ovarian cancer." (PMID 38637813, 2024). "Furthermore, we analyzed the prognostic value of ovarian cancer based on the expression level of ALKBH5 and IGF2BP2 with distinct phenotypes of macrophage expressions." (PMID 38637813, 2024). "The small molecules or drugs targeting ALKBH5 or IGF2BP2 were investigated using GDSC and CTRP database, which might help demonstrate the potential drugs that target ALKBH5 or IGF2BP2 in ovarian cancer." (PMID 38637813, 2024). "In order to investigate whether ALKBH5 and IGF2BP2 regulated the immune status of ovarian cancer by influencing the polarization of macrophages, we investigated that the correlation between ALKBH5 and IGF2BP2 with M2 macrophage polarization-related genes." (PMID 38637813, 2024). "In conclusion, our study demonstrated that ALKBH5 and IGF2BP2 were significantly up-regulated in M2 macrophages, which not only showed closely correlation with macrophage expression in ovarian cancer, but also correlated with the prognosis of ovarian cancer." (PMID 38637813, 2024). "For example, IGF2BP2 gene is a relatively common event in comparison to the amplification of the other IGF2BPs family members, IGF2BP1 and IGF2BP3, occurring in ~15–27% of ovarian cancers." (PMID 35717493, 2022). "Given the theory implicating the distal oviduct as a common source for epithelial ovarian cancer, we analyzed the GSE69428 data and showed that the expression of IGF2BP2, IGF2BP3, RBMX, YTDHF1, and RBM15 was also higher in ovarian cancer than in normal oviduct." (PMID 33225598, 2021). "Two GEO databases demonstrated that 7 readers (HNRNPC, IGF2BP1, IGF2BP2, IGF2BP3, RBMX, YTHDC2, and YTHDF2) and 3 writers (METTL3, RBM15, and RBM15B) were more highly expressed in ovarian cancer than in ovarian surface epithelium or normal peritoneum tissues (GEO14407 and GEO12470)." (PMID 33225598, 2021). "In ovarian cancer, circITGB6 promotes an M2 macrophage‐dependent cisplatin resistance by forming a circITGB6/IGF2BP2/FGF9 RNA‐protein ternary complex by directly interacting with IGF2BP2 and FGF9 mRNA, which stabilize FGF9 mRNA and induce polarization of TAMs toward M2 phenotype." (PMID 39901896, 2025). "In the ovarian cancer TCGA RNA dataset, the expression levels of exons surrounding breakpoints of IGF2BP2 and TESPA1 did not change, and the overall expression of the genes did not correlate in any patient, suggesting that we detected an uncommon, patient-specific fusion." (PMID 38012143, 2023). "Based on these analysis, we found that ALKBH5 and IGF2BP2 could regulate the immune status of ovarian cancer microenvironment mainly through its mRNA expression levels, the mutation status of ALKBH5 and IGF2BP2 might not influence the immune status of ovarian cancer." (PMID 38637813, 2024). "Thus, we assumed that ALKBH5, but not IGF2BP2 might participate in regulation the macrophages in ovarian cancer, especially by promoting the M2 polarization of macrophages." (PMID 38637813, 2024).
head and neck squamous cell carcinoma (20 papers, 2015 to 2026). A squamous cell carcinoma that arises from any of the following anatomic sites: lip and oral cavity, nasal cavity, paranasal sinuses, pharynx, larynx, and salivary glands. "Based on cases with head and neck squamous cell carcinomas from KMPLOTS database, the prognostic value of IGF2BP2 was analyzed and lower IGF2BP2 expression was linked to higher survival probability in head and neck squamous cell carcinoma patients." (PMID 37816718, 2023). "Moreover, according to The Cancer Genome Atlas dataset, high expression of the IGF2BP2 gene is associated with poor survival in patients with head and neck squamous cell carcinoma." (PMID 32784624, 2020). "IGF2BP2's pro-tumorigenic role is highly preserved in head and neck squamous cell carcinoma (HNSCC)." (PMID 41522349, 2026). "As an m6A methylation reader, IGF2BP2 triggers endothelial cell activation, facilitating angiogenesis and metastatic spread of LUAD cells, and IGF2BP2 is considered a potential immune biomarker in head and neck squamous cell carcinoma." (PMID 40236649, 2025). "IGF2BP2, an m6A “reader,” is upregulated in head and neck squamous cell carcinoma (HNSC), where it correlates with poor prognosis and regulates pathways related to cell proliferation and immune modulation." (PMID 40565233, 2025). "In head and neck squamous cell carcinoma, miR-98-5p suppresses tumor growth by downregulating IGF2BP2, which inhibits cell cycle progression while promoting apoptosis." (PMID 40530014, 2025). "In this study, lower IGF2BP2 expression was linked to higher survival probability in LSCC and other head and neck squamous cell carcinoma patients, suggesting its potential role in LSCC progression." (PMID 37816718, 2023). "Lower IGF2BP2 expression was linked to higher survival probability in LSCC and other head and neck squamous cell carcinoma patients." (PMID 37816718, 2023). "IGF2BP2 is a member of the insulin-like growth factor pathway and it has been shown that its expression correlates with tumor progression in head and neck squamous cell carcinoma patients." (PMID 25923053, 2015). "IGF2BP2 exerts a vital effect on cancer development and might act as a critical biological factor for the prognosis of head and neck squamous cell carcinomas." (PMID 37816718, 2023). "For instance, KLF7 binds to the IGF2BP2-SE to drive IGF2BP2 overexpression and promote tumor progression in head and neck squamous cell carcinoma (HNSCC), while TP63 and SOX2 co-activate SEs and the promoter of CCAT1 to drive tumorigenesis in squamous cell carcinomas (SCCs)." (PMID 41462308, 2025). "In head and neck squamous cell carcinoma (HNSC), the presence of HNRNPC, DNMT1, DNMT3A, ZC3H13, NSUN5, and IGF2BP2 highlights potential cross-talk between DNA and RNA methylation in immune modulation." (PMID 40565233, 2025). "The role of m6A readers, such as insulin-like growth factor 2 mRNA-binding protein 2 (IGF2BP2), in regulating head and neck squamous cell carcinoma (HNSCC) remains unclear." (PMID 32391379, 2020).
colon carcinoma (18 papers, 2018 to 2025). "Through positive regulation of a glycolysis-associated gene, HK2 (hexokinase 2), IGF2BP2 has been documented to control tumor metabolism in colon cancer." (PMID 38250159, 2024). "The data indicate a gradual increase in the number of patients with an IGF2BP2 autoimmune response with cancer progression, indicating that IGF2BP2 may be associated with colon cancer transformation." (PMID 29736175, 2018). "Silencing HOTAIR can inhibit the invasion, proliferation, and migration of colon cancer LoVo cells and promote cell apoptosis by inhibiting IGF2BP2 and epithelial mesenchymal transformation." (PMID 33952279, 2021). "Non-coding genes can also target IGF2BP2 directly: the lncRNA HOTAIR inhibits IGF2BP2 and regulates colon cancer growth and invasion." (PMID 32391379, 2020). "In support of this, 23.4% of colon cancer patients were found with IGF2BP2 autoantibody in their blood whereas the percentages in patients with colon adenocarcinoma and healthy population were 4.8% and 2.9%, respectively." (PMID 29736175, 2018). "A recent in vitro study demonstrated experimentally that IGF2BP2 participates in the regulation of colon cancer cell proliferation." (PMID 29736175, 2018). "Further studies in large cohorts of patients are required to dissect the correlation of IGF2BP2 autoimmune response with the stages and subcategories of colon cancer." (PMID 29736175, 2018). "For instance, lncRNA HOTAIR inhibits IGF2BP2 and regulates the growth and invasion of colon cancer." (PMID 36793593, 2023). "A decade ago, autoantibodies against IGF2BP2 were detected in the sera of colon cancer patients." (PMID 37248468, 2023). "IGF2BP2 knock-out mice possess a higher frequency of autoantibody response to IGF2BP2/p62 in colon cancer, although the mechanisms and its role in CRC carcinogenesis are still unknown." (PMID 31440515, 2019). "However, data on the impact of IGF2BP2 on chemoresistance in colon cancer has been missing so far." (PMID 37248468, 2023). "Indeed, IGF2BP2 can promote the expression of ErbB2 to repress colon cancer cells apoptosis." (PMID 35915142, 2022). "For instance, IGF2BP1 typically promotes tumor growth in breast and liver cancers, while IGF2BP2 and IGF2BP3 are involved in enhancing the proliferation and metastasis of certain cancers, such as colon cancer." (PMID 40088376, 2025). "In colon cancer, the presence of LINRIS (Long Intergenic Noncoding RNA for IGF2BP2 Stability) in large amounts maintains the stability of “reader” IGF2BP2, because the autophagy-lysosome pathway is blocked." (PMID 35590394, 2022). "Compared to normal colon tissues, a great number of m6A regulators with CNV deletions had lower expression in colon cancer tissues (for instance, ALKBH5), and vice versa (e.g., YTHDF1, IGF2BP2, HNRNPA2B1, etc.)." (PMID 36119534, 2022). "In addition, METTL3 increases the expression of PTTG3P through an m6A/IGF2BP2-dependent mechanism and regulates the PTTG3P/YAP1 axis to induce colon cancer cell proliferation and promote colon cancer progression." (PMID 35614935, 2022).
Insulin resistance (18 papers, 2014 to 2025). Increased resistance towards insulin, that is, diminished effectiveness of insulin in reducing blood glucose levels. "Transcriptome results identified many DEGs linked to insulin resistance, fatty acid β oxidation, and inflammation, including IGF2BP2, LEPR, RAP1A, SESTRIN 3, and ITLN1 that have also been reported in human T2DM." (PMID 40878918, 2025). "The IGF2BP2 rs11705701 G/A variant, situated in the -1479 locus of the promoter region, has been linked to reduced body fat and insulin resistance in Mexican Americans, elevating the susceptibility to T2DM." (PMID 39659616, 2024). "The functions of IGF2BP2 are associated with insulin resistance, and insulin regulates the EGFR gene to promote the migration of human corneal epithelial cells." (PMID 37998047, 2023). "IGF2BP2: A specific variant in the Insulin-Like Growth Factor 2 mRNA Binding Protein 2 (IGF2BP2) gene is linked to both insulin resistance and impaired insulin secretion." (PMID 37965396, 2023). "IGF2BP2 rs11705701 has been associated with low body fat, which contributes to insulin resistance and consequently T2D risk in Mexican American population." (PMID 33568150, 2021). "Insulin-like growth factor 2 mRNA-binding protein 2 (IGF2BP2) is associated with insulin resistance, lipid metabolism, and tumorigenesis." (PMID 32784624, 2020). "Studies have suggested that IGF2BP2 is associated with insulin resistance, lipid metabolism, and tumorigenesis." (PMID 32784624, 2020). "Several association studies correlated igf2bp2-SNPs more with reduced pancreatic β-cell activity than insulin resistance." (PMID 25821834, 2015). "Notably, Igf2bp2 also binds to mRNAs encoding energy metabolism effectors in human cells, and Igf2bp2 suppression in visceral or subcutaneous fat correlates with insulin resistance in diabetic patients." (PMID 35036870, 2022). "Five SNPs in three genes (rs864745 in JAZF1, rs35767 in IGF1, and rs4376068, rs4402960, and rs6769511 in IGF2BP2) contributing to insulin resistance involving lipid metabolism were genotyped." (PMID 33390804, 2021). "In the current study, we focused on SNPs of three genes (JAZF1, IGF1, and IGF2BP2) which have been shown to affect lipid metabolism and insulin resistance." (PMID 33390804, 2021). "Five SNPs in three genes (rs864745 in JAZF1, rs35767 in IGF1, and rs4376068, rs4402960, and rs6769511 in IGF2BP2) that contribute to insulin resistance involving lipid metabolism were genotyped using the MassArray method in a Chinese population." (PMID 33390804, 2021). "The associations between variants of IGF2BP2 and abdominal/visceral total fat were evidenced in Canadian Caucasians and Mexican Americans, suggesting a possible role of IGF2BP2 in insulin resistance." (PMID 25062844, 2014). "Our results revealed a significant association between rs6769511 in IGF2BP2 with T2DM, indicating that the SNP could be related to insulin resistance involving lipid metabolism." (PMID 33390804, 2021).